ABCC6 (ATP binding cassette subfamily C member 6)
Description:
[Isoform 1]: ATP-dependent transporter of the ATP-binding cassette (ABC) family that actively extrudes physiological compounds, and xenobiotics from cells. Mediates ATP-dependent transport of glutathione conjugates such as leukotriene-c4 (LTC4) and N-ethylmaleimide S-glutathione (NEM-GS) (in vitro), and an anionic cyclopentapeptide endothelin antagonist, BQ-123. May contribute to regulate the transport of organic compounds in testes across the blood-testis-barrier (Probable). Does not appear to actively transport drugs outside the cell. Confers low levels of cellular resistance to etoposide, teniposide, anthracyclines and cisplatin. [Isoform 1]: Mediates the release of nucleoside triphosphates, predominantly ATP, into the circulation, where it is rapidly converted into AMP and the mineralization inhibitor inorganic pyrophosphate (PPi) by the ecto-enzyme ectonucleotide pyrophosphatase phosphodiesterase 1 (ENPP1), therefore playing a role in PPi homeostasis. [Isoform 2]: Inhibits TNF-mediated apoptosis through blocking one or more caspases.
Synonyms: MOAT-E; ARA; MRP6; EST349056; MLP1; URG7; ABC34; GACI2; MOATE; PXE; PXE1
Tractability: Small molecule: a structure with a bound ligand is known; it belongs to a druggable protein family. Antibody: UniProt places it where antibodies can reach, with high confidence; its Gene Ontology location is reachable by antibodies, with high confidence; UniProt predicts a signal peptide or a membrane-spanning region; the Human Protein Atlas places it where antibodies can reach. PROTAC: ubiquitination databases record sites on it; its protein half-life has been measured.
Target class: ABCC subfamily; ATP-binding cassette; Transporter; Primary active transporter
Safety:
Unwanted effects reported when the protein is acted on. In parentheses: how it was acted on, where the effect was seen, and who reports it.
drug toxicity (source: ClinPGx)
Gene: Protein-coding gene on chromosome 16 (16,149,565 to 16,223,637, reverse strand). Ensembl gene ENSG00000091262.
Subcellular location: Basal cell membrane; Basolateral cell membrane (Isoform 1); Endoplasmic reticulum membrane (Isoform 2)
Subcellular location (Human Protein Atlas): Plasma membrane; Nucleoplasm
Pathways (Reactome):
Disease: Defective ABCC6 causes PXE
Transport of small molecules: ABC-family protein mediated transport
Gene Ontology:
Molecular function: ABC-type glutathione S-conjugate transporter activity; ATP binding; ATPase-coupled transmembrane transporter activity; protein binding; ABC-type transporter activity; ATP hydrolysis activity; transmembrane transporter activity
Biological process: ATP metabolic process; ATP transport; calcium ion homeostasis; gene expression; leukotriene transport; phosphate ion homeostasis; response to xenobiotic stimulus; transmembrane transport; carboxylic acid transport; inhibition of non-skeletal tissue mineralization; inorganic diphosphate transport; intracellular phosphate ion homeostasis; response to magnesium ion; response to sodium phosphate
Cellular component: basal plasma membrane; basolateral plasma membrane; extracellular region; plasma membrane; endoplasmic reticulum membrane; membrane
Genetic constraint (gnomAD): Loss-of-function variants: 126 observed, 159.35 expected, observed/expected ratio (o/e) 0.79, 90% interval 0.68 to 0.92. The upper end of that interval is the gene's LOEUF score, 0.92, which puts it in group 3 of 6, group 1 being the genes least tolerant of losing a copy. Missense variants: 1,713 observed, 1,833.9 expected, observed/expected ratio (o/e) 0.93, 90% interval 0.9 to 0.97. Synonymous variants: 741 observed, 779.65 expected, observed/expected ratio (o/e) 0.95, 90% interval 0.89 to 1.01.
Gene-disease validity (ClinGen):
ClinGen rates the evidence that ABCC6 causes each of these diseases.
inherited pseudoxanthoma elasticum (semidominant): Definitive. An inheritable form of pseudoxanthoma elasticum (PXE), that causes calcium and other minerals to accumulate in the elastic fibers of the skin, eyes, and blood vessels, and less frequently in other areas such as the digestive tract.
Homologues: Orthologues: chimpanzee ABCC6 (99% identical), macaque ABCC6 (96% identical), pig ABCC6 (84% identical), rabbit ABCC6 (81% identical), dog ABCC6 (81% identical), mouse Abcc6 (79% identical), rat Abcc6 (79% identical), guinea pig ABCC6 (76% identical), tropical clawed frog abcc6 (41% identical), Drosophila melanogaster MRP (38% identical), Drosophila melanogaster Mrp5 (27% identical), Drosophila melanogaster CG11898 (27% identical), and 9 more. Paralogues in human: ABCC1 (46% identical), ABCC3 (43% identical), ABCC2 (38% identical), ABCC8 (30% identical), ABCC10 (30% identical), ABCC9 (30% identical), ABCC5 (29% identical), ABCC4 (28% identical), ABCC11 (26% identical), ABCC12 (26% identical), CFTR (23% identical).
Diseases named in the same sentence as ABCC6 in open-access papers:
ABCC6 is named in the same sentence as 146 diseases in open-access papers, as found by Europe PMC text mining. Sharing a sentence is not in itself a finding about the gene and the disease. The quoted sentences say what the papers report.
Pseudoxanthoma elasticum (156 papers, 2007 to 2026). "Genetic variation in ATP Binding Cassette Subfamily C Member 6 (ABCC6) can cause both pseudoxanthoma elasticum (PXE) and generalized arterial calcification of infancy (GACI)." (PMID 41751966, 2026). "Pseudoxanthoma elasticum (PXE) is driven primarily by biallelic ABCC6 variants, with overlapping ectopic-mineralization phenotypes from ENPP1 and GGCX." (PMID 41511357, 2026). "Pseudoxanthoma elasticum (PXE) is a rare genetic disorder caused by mutations in the ABCC6 gene, leading to calcification of elastic and collagen fibers in connective tissues." (PMID 39913163, 2025). "Mutations in ABC transporters are etiological drivers of rare monogenic diseases with a cardiovascular component, such as Pseudoxanthoma Elasticum caused by mutations in ABCC6 and Tangier disease caused by mutations in ABCA1." (PMID 41252867, 2025). ",33, 34, 35 Of interest, however, ABCC6, which is associated with pseudoxanthoma elasticum was identified to have the second largest areas of hypo-AF." (PMID 39896422, 2025). "ABCC6 belongs to the multidrug resistance-associated family of ATP-binding cassette transporters and is best known for its role in pseudoxanthoma elasticum (PXE), an autosomal recessive disorder characterized by ectopic calcification." (PMID 40758858, 2025). "Mutations in ABCC6 are associated with pseudoxanthoma elasticum, affecting elastic fibers in tissues." (PMID 40004483, 2025). "PSVs in ABCC6 can be implicated in pseudoxanthoma elasticum (PXE), a genetic disorder characterized by calcifications in many organs/systems, including cardiovascular system, and in the generalized arterial calcification of infancy (GACI)." (PMID 40565367, 2025). "The identification of disease-causing mutations in ABCC6 as the cause of pseudoxanthoma elasticum (PXE) and the recent characterization of its function has provided a wealth of new information on the molecular pathways regulating soft tissue calcification." (PMID 38392293, 2024). "Dysfunction of ABCC6 is the primary cause of pseudoxanthoma elasticum and generalized arterial calcification of infancy (GACI)." (PMID 39526184, 2024). "The ABCC6 gene encodes ATP binding cassette subfamily C member 6, which is associated with transporter activity, and is a known causal gene of pseudoxanthoma elasticum." (PMID 38791485, 2024). "– Pseudoxanthoma elasticum (PXE) is a rare genetic disease caused by pathogenic mutations in the ABCC6 gene, resulting in low values of inorganic pyrophosphate (PPi)." (PMID 38221909, 2024). "Pseudoxanthoma elasticum (PXE) is a genetic metabolic disease with autosomal recessive inheritance caused by mutations in the ABCC6 gene." (PMID 39104655, 2024). "Because chronic ABCC6 deficiency leads to pseudoxanthoma elasticum and urolithiasis in humans, further studies will also have to confirm the protective role of transient ABCC6 inhibition on kidney dysfunction." (PMID 38057332, 2023). "The ENPP1 inactivation mutation has been identified as a potential defect in most of the cases of GACI, while mutations in ABCC6 are demonstrated in patients who are genotyped as pseudoxanthoma elasticum and only limited cases of GACI are reported." (PMID 38248755, 2023). "We found a 59-year-old man proband who had basilar artery atherosclerotic infarction as well as peripheral artery occlusive disease, carrying the heterozygous ABCC6 p.R1235W variant, which is known to be pathogenic for pseudoxanthoma elasticum." (PMID 36580209, 2023). "Another interesting candidate in Patients 1 and 2 is a heterozygous variant in ABCC6 (p.Arg1164Gln), a gene known to cause multisystemic disease affecting tissues rich in elastic fibers as the cardiovascular system called Pseudoxanthoma Elasticum (PXE)." (PMID 37298070, 2023).
Pseudoxanthoma elasticum (continued). "Mutations in ABCC6 are a major pathogenic factor in the development of pseudoxanthoma elasticum (PXE), a heritable connective tissue disorder characterized by the calcification of elastic fibers in the skin, arteries, and retina." (PMID 36465446, 2022). "Pseudoxanthoma elasticum (PXE)—a heritable ectopic mineralization disorder—is caused by mutations in the ATP-binding cassette subtype C number 6 (ABCC6) gene primarily expressed in the liver and kidneys." (PMID 35269691, 2022). "Pathogenic variants of ABCC6 cause pseudoxanthoma elasticum, a highly variable recessive ectopic calcification disorder." (PMID 36317459, 2022). "Mutations in ABCC6 result in pseudoxanthoma elasticum (PXE), a progressive human metabolic disorder characterized by mineralization of the skin and elastic tissues." (PMID 35186933, 2022). "The homozygous variant c.1171A>G p.(Arg391Gly) in ABCC6 has been previously associated with pseudoxanthoma elasticum." (PMID 34148116, 2022). "Mutations in the ABCC6 gene are associated with pseudoxanthoma elasticum (PXE), an autosomal recessive disease characterized by a progressive ectopic calcification of elastic fibers in dermal, ocular, and vascular tissues." (PMID 35645325, 2022). "Pseudoxanthoma elasticum (PXE) is an ectopic calcification disorder caused by biallelic mutations in the ABCC6 (ATP-Binding Cassette, subfamily C member 6)–and in rare cases the ENPP1 (Ectonucleotide Pyrophosphatase/Phosphodiesterase 1)–gene." (PMID 35317004, 2022). "Loss-of-function variants in ABCC6 also cause pseudoxanthoma elasticum (PXE; OMIM 264800), an autosomal recessive disorder characterized by late-onset yet progressive ectopic calcification in the skin, eyes, and arterial blood vessels." (PMID 35482848, 2022). "Pseudoxanthoma elasticum is a rare autosomal recessive disorder, which is caused by ABCC6 mutation and consequently ABCC6 protein deficiency." (PMID 35052389, 2021). "Inactivating mutations in ABCC6 underlie the rare hereditary mineralization disorder pseudoxanthoma elasticum." (PMID 34199119, 2021). "Genetic studies link adenosine triphosphate-binding cassette transporter C6 (ABCC6) mutations to pseudoxanthoma elasticum (PXE)." (PMID 33483533, 2021). "Copy number variation in the human ABCC4 and ABCC6 genes is associated with susceptibility to esophageal squamous cell carcinoma and to the rare autosomal recessive disease pseudoxanthoma elasticum, respectively." (PMID 32770942, 2020). "Pseudoxanthoma elasticum (PXE) is a rare autosomal-recessive disorder that is mainly caused by mutations in the ATP-binding cassette sub-family C member 6 (ABCC6) gene." (PMID 33352936, 2020). "Pseudoxanthoma elasticum (PXE) caused by mutations in the ATP-binding cassette sub-family C member 6 (ABCC6) gene shares some molecular characteristics with such premature aging diseases." (PMID 32489700, 2020). "Pseudoxanthoma elasticum (PXE) is a monogenetic disorder in which mutations in the ABCC6 gene result in calcification and fragmentation of elastin fibers in the skin, the Bruch’s membrane of the eyes, and the internal elastic lamina of the peripheral arteries." (PMID 32859086, 2020). "Pseudoxanthoma elasticum is a rare disease mainly due to ABCC6 gene mutations and characterized by ectopic biomineralization and fragmentation of elastic fibers resulting in skin, cardiovascular and retinal calcifications." (PMID 31861118, 2019). "Mutations in the ABCC6 gene cause pseudoxanthoma elasticum, a metabolic disease with progressive soft tissue calcification." (PMID 30611276, 2019). "Pseudoxanthoma elasticum (PXE) is an inherited metabolic disease with autosomal recessive inheritance caused by mutations in the ABCC6 gene." (PMID 28891970, 2017). "Pseudoxanthoma elasticum (PXE) is an autosomal-recessive mineralisation disorder caused by loss of function mutations in the ABCC6 Gen." (PMID 27622520, 2016).
Pseudoxanthoma elasticum (continued). "A notable example of this type of investigation was the mapping of disease associated mutations to the homology model of human ABCC6, which is responsible for pseudoxanthoma elasticum (PXE)." (PMID 26986070, 2016). "Mutations in ABCC6 (ATP-binding cassette, subfamily C, member 6), an orphan transporter expressed in the liver, are the cause of pseudoxanthoma elasticum." (PMID 25893161, 2015). "Mutations in the ABCC6 gene cause pseudoxanthoma elasticum (PXE), an autosomal recessive connective tissue disease characterized by ectopic mineralization of the elastic fibers." (PMID 25062064, 2014). "The results of such research can provide the basis of future allele-specific therapy of ABCC6-mediated disorders like pseudoxanthoma elasticum or the generalized arterial calcification in infancy." (PMID 23483032, 2013). "Screening of the adenosine triphosphate binding cassette transporter protein subfamily C member 6 gene (ABCC6) in pseudoxanthoma elasticum (PXE) revealed a mutation detection rate of approximately 87%." (PMID 23802012, 2013). "Loss-of-function mutations in ABCC6 can cause chronic or acute forms of dystrophic mineralization described in disease models such as pseudoxanthoma elasticum (OMIM 26480) in human and dystrophic cardiac calcification in mice." (PMID 21935449, 2011). "It is noteworthy to highlight that both mRNA and protein of ABCC6, causative of the pseudoxanthoma elasticum, have been identified in leukocytes, macrophages, and lymphocytes, and that all these white blood cells abundantly contain MMP-9." (PMID 19828023, 2009). "Mutations of the ABCC6 gene causethe pseudoxanthoma elasticum (PXE) (OMIM 177850 and264800), amultisystemdisorder characterized by progressivecalcification and degeneration of elastic fibers." (PMID 21318057, 2008). "ABCC5 can therefore be added to the list of abundant ABC transporters with a function in the eye which for example includes ABCA4, the gene underlying Stargardt's disease and ABCC6, the gene implicated in pseudoxanthoma elasticum." (PMID 17521428, 2007). "For instance, we found carriers of 16p13.11 deletions affecting ABCC6, the causal gene for pseudoxanthoma elasticum, to be at increased risk for kidney stones, paralleling reports from clinical cohorts showing that kidney stones represent an unrecognized feature of the disease." (PMID 38185688, 2024). "In 1 individual, homozygosity for ABCA4 c.5882G>A; p.(Gly1961Glu) as well as ABCC6 (NM_001171.6) c.708_709dup9; p.(Trp237SerfsTer22) variants resulted in a macular dystrophy phenotype as well as pseudoxanthoma elasticum, with both ocular and dermatological features noted." (PMID 38219857, 2024). "A wide range of variants affecting ABCC6 have been identified and linked to the calcification disorder pseudoxanthoma elasticum through recessive [MIM: 264800]—and more rarely dominant [MIM: 177850]—inheritance, with the Alu-mediated cat5 deletion representing one of the most frequent variants." (PMID 38185688, 2024). "Indeed, Patient 46 presents GJB2-associated HL and RPGR-associated retinitis pigmentosa while Patient 50 is affected by WFS1-related HL and pseudoxanthoma elasticum due to an ABCC6 mutation." (PMID 36979683, 2023). "Pseudoxanthoma elasticum is an inherited elastic fiber disorder usually caused by ABCC6 variants in an autosomal recessive inheritance pattern, but heterozygous carriers may express partial phenotypes." (PMID 36580209, 2023). "On the other hand, loss of ABCC6, the transporter that carries ATP outside the cell required for pyrophosphate generation causes pseudoxanthoma elasticum, a condition associated with peripheral artery calcification that does not appear to predispose to osteoporosis." (PMID 34760935, 2021).